PAX2 (paired box 2)
Description:
Transcription factor that may have a role in kidney cell differentiation. Has a critical role in the development of the urogenital tract, the eyes, and the CNS.
Synonyms: PAX-2; FSGS7; PAPRS
Tractability: No criterion of Open Targets' tractability assessment is met for any kind of drug.
Gene: Protein-coding gene on chromosome 10 (100,735,396 to 100,829,944, forward strand). Ensembl gene ENSG00000075891.
Subcellular location: Nucleus
Subcellular location (Human Protein Atlas): Nucleoplasm
Pathways (Reactome):
Developmental Biology: Formation of intermediate mesoderm; Formation of the nephric duct; Formation of the ureteric bud; Nephron development
Gene Ontology:
Molecular function: cis-regulatory region sequence-specific DNA binding; DNA binding; DNA-binding transcription factor activity; protein binding; sequence-specific double-stranded DNA binding; transcription cis-regulatory region binding; transcription factor binding; DNA-binding transcription factor activity, RNA polymerase II-specific; RNA polymerase II cis-regulatory region sequence-specific DNA binding
Biological process: branching involved in ureteric bud morphogenesis; metanephric epithelium development; negative regulation of apoptotic process; negative regulation of DNA-templated transcription; negative regulation of reactive oxygen species metabolic process; positive regulation of DNA-templated transcription; positive regulation of epithelial cell proliferation; positive regulation of transcription by RNA polymerase II; regulation of metanephros size; axonogenesis; brain morphogenesis; camera-type eye development; cell fate determination; cellular response to glucose stimulus; cellular response to retinoic acid; cochlea development; cochlea morphogenesis; glial cell differentiation; inner ear morphogenesis; mesenchymal to epithelial transition; mesenchymal to epithelial transition involved in metanephros morphogenesis; mesodermal cell fate specification; mesonephros development; metanephric collecting duct development; metanephric distal convoluted tubule development; and 32 more
Cellular component: centriolar satellite; microtubule organizing center; nucleoplasm; nucleus; chromatin; protein-containing complex; protein-DNA complex
Genetic constraint (gnomAD): Loss-of-function variants: 11 observed, 40.37 expected, observed/expected ratio (o/e) 0.27, 90% interval 0.17 to 0.45. The upper end of that interval is the gene's LOEUF score, 0.45, which puts it in group 2 of 6, group 1 being the genes least tolerant of losing a copy. Missense variants: 418 observed, 537.06 expected, observed/expected ratio (o/e) 0.78, 90% interval 0.72 to 0.84. Synonymous variants: 221 observed, 218.76 expected, observed/expected ratio (o/e) 1.01, 90% interval 0.9 to 1.13.
Gene-disease validity (ClinGen):
ClinGen rates the evidence that PAX2 causes each of these diseases.
focal segmental glomerulosclerosis 7 (autosomal dominant): Definitive. Any focal segmental glomerulosclerosis in which the cause of the disease is a mutation in the PAX2 gene.
Homologues: Orthologues: chimpanzee PAX2 (100% identical), pig PAX2 (99% identical), dog PAX2 (99% identical), rabbit PAX2 (99% identical), mouse Pax2 (99% identical), rat Pax2 (95% identical), tropical clawed frog pax2 (90% identical), guinea pig PAX2 (89% identical), zebrafish pax2a (88% identical), macaque PAX2 (87% identical), zebrafish pax2b (86% identical). Paralogues in human: PAX5 (71% identical), PAX8 (62% identical), PAX7 (40% identical), PAX3 (38% identical), PAX1 (35% identical), PAX9 (35% identical), PAX4 (27% identical), PAX6 (18% identical), ARX (14% identical), EVX2 (14% identical), UNCX (13% identical), RAX (13% identical), and 38 more.
Diseases named in the same sentence as PAX2 in open-access papers:
PAX2 is named in the same sentence as 219 diseases in open-access papers, as found by Europe PMC text mining. Sharing a sentence is not in itself a finding about the gene and the disease. The quoted sentences say what the papers report.
renal coloboma syndrome (45 papers, 2010 to 2026). Renal coloboma syndrome (RCS) is a genetic condition characterized by optic nerve dysplasia and renal hypodysplasia. "Papillorenal syndrome mainly manifests by ocular and renal abnormalities due to heterozygous pathogenic PAX2 gene variants." (PMID 40282888, 2025). "This molecular study revealed a heterozygous allele in PAX2, c.8T>C or p.(Met3Thr), which attracted our attention because this gene has been implicated in papillorenal syndrome (PAPRS)." (PMID 38909058, 2024). "For instance, in renal coloboma syndrome, also known as papillorenal syndrome, 50% of cases are associated with PAX2 mutations." (PMID 39594614, 2024). "PAX2 haploinsufficiency is known to be associated with papillorenal syndrome in humans (MIM #120330), which comprises a CAKUT phenotype with eye anomalies." (PMID 38154558, 2024). "Pathogenic variants in PAX2 commonly result in the papillorenal syndrome which more typically manifests as CAKUT with ocular anomalies." (PMID 37578539, 2024). "In humans, PAX2 mutations cause renal coloboma syndrome, an autosomal dominant condition characterized by kidney abnormalities, optic nerve colobomas and hearing loss." (PMID 38353121, 2024). "Optic nerve dysplasia also described as ‘optic nerve coloboma’ or a ‘morning glory disc anomaly’ is typical of papillorenal syndrome due to PAX2 pathogenic variants." (PMID 37468646, 2024). "PAX2 heterozygous mutations were described for the first time in 1995 in patients presenting renal coloboma syndrome." (PMID 37628926, 2023). "The first reported cases described with the PAX2 mutation included both renal anomalies and the involvement of other organs, such as the eyes, producing renal coloboma syndrome." (PMID 37628926, 2023). "The clinical diagnosis of two brothers referred with familial juvenile hyperuricemic nephropathy was revised to papillorenal syndrome following identification of a PAX2 pathogenic variant, a diagnosis which was confirmed by ophthalmological investigations." (PMID 37946251, 2023). "WES revealed a novel PAX2 frameshift variant (NM_003990.5: c.124_139del; p.Val42Argfs*36), confirming the diagnosis of papillorenal syndrome (MIM 120,330, up to 60 patients reported worldwide)." (PMID 34217267, 2021). "PAX2 is a transcription factor essential for kidney development and the main causative gene for renal coloboma syndrome (RCS)." (PMID 33907292, 2021). "Out of the 12 families of ESRDu, we detected the biallelic variants of NPHP3 in one family and the heterogeneous variant in PAX2 in the second family confirming the diagnosis of renal coloboma syndrome." (PMID 34215756, 2021). "Among these, 3 diseases have AD inheritance: ADTKD-UMOD, Ayme-Gripp syndrome due to MAF mutation, and papillorenal syndrome due to PAX2 mutation." (PMID 34217267, 2021). "Pathogenic variants of PAX2 cause autosomal-dominant PAX2-related disorder, which includes variable phenotypes ranging from renal coloboma syndrome (RCS), congenital anomalies of the kidney and urinary tract (CAKUT) to nephrosis." (PMID 34696790, 2021). "Two patients with bilateral renal hypodysplasia and optic nerve anomalies carried variants in PAX2 (p.Arg115Pro and p.Val26Glyfs*28, respectively), causing renal coloboma syndrome." (PMID 32164334, 2020). "PAX2 mutations are associated with renal coloboma syndrome (RCS), which is characterized by abnormalities in renal structure and function, and anomalies of the optic nerve." (PMID 32776440, 2020). "An elegant and phenotypically relevant example is that reciprocal inhibition between Pax6 and Pax2 establishes the retinal-optic nerve boundary in mammals; PAX2 mutation causes papillorenal syndrome in humans (MIM #120330)." (PMID 30242502, 2019). "The most common renal phenotype caused by mutation of PAX2 is renal coloboma syndrome (OMIM #120330; also known as papillorenal syndrome)." (PMID 30241513, 2018).
renal coloboma syndrome (continued). "Mutations in PAX2 have been implicated in retinal colobomas, including the papillorenal syndrome (PAPRS, MIM120330)." (PMID 28855599, 2017). "The PAX2 gene is associated with the renal coloboma syndrome (MIM 120330), a syndrome characterized by renal hypoplasia and insufficiency, vesicoureteric reflux, and optic disc coloboma." (PMID 21995344, 2011). "Paired paired box protein 2 (PAX2) gene variant causes renal coloboma syndrome (RCS, MIM#120330)." (PMID 37897632, 2024). "Paired box protein 2 (PAX2) gene variant causes renal coloboma syndrome (MIM#120330)." (PMID 37897632, 2024). "In the following decade, most PAX2-related disorders were associated with renal coloboma syndrome." (PMID 37628926, 2023). "Heterozygous variants in PAX2 were first identified in 1995 in patients with renal coloboma syndrome (RCS, also known as “papillorenal syndrome”, MIM #120330), which is a rare autosomal dominant disorder characterized by renal hypodysplasia (RHD) and retinal coloboma (HP:0000480)." (PMID 34696790, 2021). "Mutations in PAX2 were identified in individuals with ocular coloboma in renal coloboma syndrome." (PMID 21655361, 2011). "We note that several of the highly correlated genes-SALL4 (Duane-Radial Ray Syndrome), PAX2 (Papillorenal syndrome), ACGT1 (Baraitser-Winter Syndrome 2), SALL1 (Townes-Brocks Syndrome 1) can also present with congenital renal anomalies." (PMID 40610405, 2025). "PAX2-related disorders encompass renal coloboma syndrome (RCS) and hereditary focal segmental glomerulosclerosis (FSGS) type 7." (PMID 39994403, 2025). "We note that several of the enriched genes-SALL4 (Duane-Radial Ray Syndrome), PAX2 (Papillorenal syndrome), ACGT1 (Baraitser-Winter Syndrome 2), SALL1 (Townes-Brocks Syndrome 1) can also present with congenital renal anomalies." (PMID 39606382, 2024). "These include Dent disease (CLCN5, OCRL), AD tubulointerstitial kidney disease (ADTKD due to UMOD variants), nephronophthisis (TTC21B, NPHP4), Imerslund-Grasbeck syndrome 1 (CUBN) and papillorenal syndrome (PAX2)." (PMID 37578539, 2024). "For instance, it has been shown that PAX2 haploinsufficiency is commonly found in patients with papillorenal syndrome (PAPRS, OMIM #120330)." (PMID 36835576, 2023). "PAX2-related disorder was originally termed renal coloboma syndrome (also known as papillorenal syndrome) and characterized by renal (hypodysplastic kidneys) and optic disc anomalies." (PMID 32111086, 2020). "Some syndromic CAKUT encompass characteristic extrarenal manifestations, such as hearing loss and neck anomalies in BOR syndrome (EYA1), optic nerve coloboma in renal coloboma syndrome (PAX2), and hyperuricemia and diabetes in RCAD syndrome (HNF1B)." (PMID 32164334, 2020). "Only a few mouse mutant lines are known like the Pax2 mutants suffering from the renal coloboma syndrome, because Pax2 is expressed not only in the developing eye, but also in the kidney leading eventually to defects in both organs, if mutated." (PMID 30919050, 2019). "Some of these are included in complex clinical syndromes such as branchio-oto-renal syndrome (EYA1, SIX1), renal-coloboma syndrome (PAX2), renal cysts and diabetes syndrome (TCF2/HNF1B) and Townes–Brocks syndrome (SALL1)." (PMID 28647851, 2018). "Pathogenic variants in PAX genes underlie diverse congenital disorders such as aniridia (PAX6), renal coloboma syndrome (PAX2), otofaciocervical syndrome with immunodeficiency (PAX1), Waardenburg syndrome (PAX3), maturity-onset diabetes of the young (PAX4), and tooth agenesis (PAX9)." (PMID 41751498, 2026). "PAX2 variants, particularly loss-of-function (LOF) variants, can cause congenital anomalies of the kidney and urinary tract (CAKUT), mostly associated with renal coloboma syndrome (RCS), and focal segmental glomerulosclerosis (FSGS) marked by proteinuria." (PMID 41278353, 2025).
renal coloboma syndrome (continued). "Mutations in PAX2 were previously associated with rare congenital abnormalities of the kidney and urinary tract (CAKUT) and with renal coloboma syndrome (RCS), while little was known about the effects of PAX2 mutations in diseases affecting the glomerular components of the kidney." (PMID 34944624, 2021). "Patients with a homozygous variant of PAX2 die soon after birth due to the lack of organogenesis; in contrast, patients with a heterozygous variant of PAX2 may present with renal coloboma syndrome (RCS) and FSGS." (PMID 35444690, 2022). "Although renal coloboma syndrome (RCS) with simultaneous kidney and eye involvement is the most common phenotype of PAX2 mutations, current literature supports that such mutations may have profuse clinical manifestations and renal hypoplasia is one distinct entity in the spectrum." (PMID 30241513, 2018). "Clinical manifestation of renal coloboma syndrome with/without PAX2 mutation." (PMID 26571382, 2015). "The WES approach allowed us to identify five clinically relevant variants in the GZF1, NFIX, TRRAP, FGFR2 and PAX2 genes associated with Larsen, Malan, developmental delay with or without dysmorphic facies and autism, LADD1 and papillorenal syndromes." (PMID 38909058, 2024). "Renal coloboma syndrome (RCS, MIM#120330) with or without vesicoureteral reflux (VUR), also known as PAX2‐related disorder, is associated with PAX2 mutation." (PMID 31060108, 2019).
coloboma (23 papers, 2006 to 2025). An abnormality in which a part of a structure in one or both eyes is missing. "Pax2 mutations and loss of function are associated with coloboma or microphthalmia, both of which are consequences of eye morphogenesis defects." (PMID 37452018, 2023). "When a pathogenic variant is found in certain genes, screening for ocular coloboma or diabetes caused by PAX2 or HNF1B respectively, should be recommended." (PMID 36939782, 2021). "Alteration of PAX2 function is a common cause of coloboma and studies in mouse and zebrafish models have highlighted its function in morphogenetic events required for optic fissure closure." (PMID 24412933, 2014). "The correct patterning of the optic fissure is dependent on the actions of Bmp7 and Shh and mutations in Pax2 and Vax1 lead to a deficiency in the closure of the optic fissure, a condition known as coloboma." (PMID 20386732, 2010). "Ocular coloboma is a ventral patterning defect has been shown to be associated with abnormal Pax2 and Vax expression." (PMID 20485507, 2010). "Interestingly, PAX2, which when mutated is known to cause ocular coloboma in humans and zebrafish, was upregulated in mouse, chicken, and zebrafish fissures and was highly specific to the pioneer cell region of the retina." (PMID 36830662, 2023). "The involvement of Pax2 in an Nr2f1-regulated network is particularly important, as human PAX2 mutations lead to coloboma-like OD malformations in the context of syndromic conditions, consistent with a key role of the Nr2f1-Pax2-Pax6 genetic network for the correct establishment of the OD region." (PMID 35455940, 2022). "However, correct regulation of cell death has been shown to be vital for OFC in zebrafish and to be a downstream effect of the important coloboma-associated transcription factors PAX2 and VAX." (PMID 33505973, 2020). "Loss of Pax2 in mice leads to a coloboma phenotype due to inability of the edges of the OF to fuse." (PMID 28729440, 2017). "The coloboma scores were significantly higher in patients with PAX2 mutations." (PMID 26571382, 2015). "However, the degree of kidney dysfunction and coloboma varied, even among patients with the same PAX2 mutation." (PMID 26571382, 2015). "Jnk1−/− Jnk2−/+ mice (lacking activity of members of the Jun N-terminal Kinase, JNK, group of mitogen activated kinases) exhibit coloboma associated with loss of Shh and Bmp4 signaling, and reduced levels of Pax2, while addition of Bmp4 restored Shh and Pax2 expression." (PMID 24412933, 2014). "Our findings also refuted the alternative model of coloboma caused by disruption of PAX2 function by showing normal localization of PAX2 in the cells encircling the optic disc and normal dissolution of the basal lamina, which requires PAX2, in the Sall2-deficient eyes." (PMID 24412933, 2014). "However, it has also been shown that ectopic expression of Pax2 in the ventral optic cup after electroporation in the chick can leads to a failure of choroid fissure closure, phenocopying the colobomas seen with Pax2 loss of function." (PMID 20485507, 2010). "Lack of Pax2 expression results in persistence of the basal lamina and matrix at the sides of the choroid fissure, preventing the fusion of the neuroepithelium and causing coloboma." (PMID 20485507, 2010). "As colobomas have been previously associated with abnormal Pax2 expression, we hypothesized that Pax2 expression could be dysregulated in the region of the choroid fissure in the morphant larvae." (PMID 20485507, 2010).